KEAP1 (kelch like ECH associated protein 1)
Diseases named in the same sentence as KEAP1 in open-access papers (continued):
Sharing a sentence is not in itself a finding about the gene and the disease.
tumor (continued). "The authors concluded that KRAS mutations could be associated with improved survival in NSCLC patients treated with immunotherapy in the absence of mutations in the STK11 and KEAP1 genes in tumor cells." (PMID 37509393, 2023). "Previous studies have also suggested that some genetic alterations in the tumor cells, such as somatic mutations in serine/threonine kinase 11 (STK11) or in kelch-like ECH-associated protein 1 (KEAP1), could serve as biomarkers to predict responses to ICIs in NSCLC." (PMID 36835030, 2023). "Therefore, it is reasonable to make the deduction that tumor cell response to CDDP-based chemotherapy might be overcome by targeting the KEAP1/NRF2-mediated disturbance of ferroptosis, as presented and verified in this study." (PMID 35505963, 2022). "While KEAP1 and/or FSP1 deletion did not obviously affect cell proliferation in H1299 cells, loss of KEAP1 significantly accelerated H1299 xenograft tumor growth, which is consistent with previous reports; importantly, FSP1 deletion markedly suppressed KEAP1 KO tumor growth." (PMID 35459868, 2022). "Among the others, the genetic background, the subcellular location, the presence of genetic polymorphisms, the interactions with upstream and downstream regulators and the KEAP1 status represent the major determinants of whether NRF2 will exert tumor-promoting or tumor-suppressive functions." (PMID 33805996, 2021). "Furthermore, wild-type KEAP1 tumor cells may be sensitized to ASNase treatment by induction of oxidative stress." (PMID 34267184, 2021). "Finally, one patient harboring KEAP1 mutation along with a lack of immune cells infiltration in tumor microenvironment failed to respond to checkpoint inhibitor despite high tumor mutational burden (TMB)." (PMID 34328274, 2021). "Notably, mutations in NFE2L2, KEAP1 and CUL3 that cause persistent upregulation of NRF2 often co-exist with mutations that activate KRAS and the PI3K-PKB/Akt pathway, suggesting NRF2 supports growth of tumours in which KRAS or PKB/Akt are hyperactive." (PMID 33276631, 2020). "The finding that KEAP1 transcript levels are modulated by methylation only in KRAS wild-type NSCLC might indicate that methylation is a KRAS-independent mechanism to modulate NRF2 levels in tumor cells." (PMID 32971994, 2020). "However, systemic or kidney-specific deletion of the Keap1 gene is not sufficient to cause an aggressive tumor formation, suggesting that NRF2 plays a role in supporting tumor growth and drug resistance, but not in tumorigenesis." (PMID 33233657, 2020). "Indeed, specific inhibitors targeting the interaction between P-p62 and Keap1, opposing tumor cells proliferation and chemoresistance have been proposed as treatment for HCC, and could be exploited also in other tumor types featuring NRF2 hyperactivation." (PMID 33233657, 2020).
tumor (continued). "In the subnetwork related to tumor progression, the hubs from the blue module are the most connected, such as the genes Cmas, Kmt2a, Golt1b, Cdc34, Manf, Sco1, and Thoc3, followed by hubs from the light cyan (Extl2, Commd3, Wdr41, Keap1, Osbpl9) and pink modules." (PMID 32831131, 2020). "The discrepancy from normal in the Keap1-Nrf2 pathway may lead to promotion of tumor." (PMID 29484121, 2018). "All these occur in human cancer and hence Keap1 may act as tumour suppressor." (PMID 30513925, 2018). "Firstly, it is natural to wonder what the real role of P1 CpG island methylation is and if the methylation status of KEAP1 exclusively affects its expression or could additionally interfere with the ability to bind to NRF2 in promoting tumor progression and resistance to therapies." (PMID 29643973, 2018). "Furthermore, the assessment of AKR levels potentially constitutes a means to discriminate between the relative functionality of KEAP1 and NRF2 mutations and, ultimately, whether they are likely to influence tumour phenotype." (PMID 27824809, 2016). "Furthermore, we identify a novel compound that inhibits Nrf2 activity by preventing the interaction between phosphorylated p62 and Keap1, and may have potential as an anti-tumour drug." (PMID 27345495, 2016). "Heme oxygenase 1 (Hmox1) plays an important role in the growth and spread of tumor, and its expression is regulated positively by Nrf2 [nuclear factor (erythroid-derived 2)-like 2; NFE2L2] and negatively by kelch-like ECH-associated protein 1 (Keap1) and by BTB and CNC homology 1 (Bach1)." (PMID 27999449, 2016). "Moreover, RTA 405 also directly inhibits IKKβ and decreases NF-κB activity, as evidenced by reduced Ccnd1 levels in Keap1-/- MEFs The decrease in NF-κB activity may suppress tumor cell survival and promote apoptosis." (PMID 26301506, 2015). "Ginsenoside Rh4 induces ferroptosis by inhibiting the KEAP1/NRF2/HO-1 pathway and remodeling the gut microbiota to increase butyrate levels, which synergistically enhance tumor cell ferroptosis sensitivity through ATF3 activation and suppression of GPX4." (PMID 41898564, 2026). "Notably, Eno (100 μg/mL) combined with sorafenib (2 μM) had a synergistic anti-tumor effect (Q = 1.47), which further enhanced the inhibition of HepG2 cell growth and metastasis, aggravated ferroptosis, and more strongly suppressed the p62/Keap1/Nrf2/HO-1 axis." (PMID 42042017, 2026). "Compared with those in normal tissue, KEAP1, STK11, and CDKN2A were highly expressed in the tumor samples of NSCLC patients (P < 0.01)." (PMID 41491583, 2026). "Our study highlights the potential of IFNG, KEAP1, and PHKG2 as predictive markers for T cell infiltration and the tumor microenvironment status in OV." (PMID 40744688, 2025). "Previous studies have shown that SOX9 can be ubiquitinated by the E3 ligases KEAP1 or FBXW7, leading to its proteasomal degradation and consequent suppression of tumor progression." (PMID 41428171, 2025). "Higher magnification images further clarified that, while many CD45-positive cells resided in the stroma areas of the WT tumor tissues, much fewer CD45-positive cells were found in the stroma areas of the KEAP1-KO tumor tissues." (PMID 41035689, 2025). "In conclusion, we demonstrated that itaconate reduces the sensitivity of tumor cells by stabilizing the NRF2 protein, which is dependent on KEAP1." (PMID 40482348, 2025). "KEAP1/NRF2 dysregulation enhances antioxidant defenses and enables tumor cells to resist reactive oxygen species‐induced apoptosis." (PMID 40145314, 2025).
tumor (continued). "IHC staining of HCC organoids and the corresponding primary tumor tissues showed that lenvatinib‐resistant organoids and tumor tissues exhibited elevated expression levels of HECTD2 and NRF2, along with reduced KEAP1 expression." (PMID 39976163, 2025). "However, as KEAP1 mutations frequently co-occur with STK11 mutations in clinical samples, which is also known to modulate the tumor immune milieu, these clinical observations suggest that NRF2 may act collaboratively with STK11 to cause the lower-level immune cell infiltrations in the tumors." (PMID 41035689, 2025). "Immunohistochemical analysis showed that high NQO1 expression in the tumor area of the KEAP1-KO tumor tissues was reversed in that of the DKO tumor tissues." (PMID 41035689, 2025). "By contrast, very low NQO1 expression was found in the tumor area of the DKO tumor tissues, indicating that NRF2 activation in the KEAP1-KO tumor is efficiently canceled in the DKO tumor tissues." (PMID 41035689, 2025). "In ovarian tumor (OT) tissues, DHT enhances the binding of NRF2 to Keap1, resulting in potentiated ubiquitination and degradation of NRF2, thereby activating oxidative stress and exhibiting anti-tumor effects." (PMID 40258841, 2025). "Taken together, these findings are evidence of a shift in the KEAP1 KO TIME, from immunosuppressive to anti-tumor, an effect common between omaveloxolone and CDDO-Me." (PMID 41462606, 2025). "In prostate cancer, for example, the activity of the Nrf2/Keap1 system is modulated by upstream oncogenic signals, including KRAS and Myc, which influence its dual role in tumor suppression and progression depending on the cellular context." (PMID 40867898, 2025). "The interaction of CDK20 with KEAP1, confirmed by co-immunoprecipitation of endogenous proteins in HEK293T cells, enables NRF2 activation, helping tumor cells survive therapy-induced stress." (PMID 39941813, 2025). "Tumor extracts from doxycycline-treated mice were compared with those from untreated mice, confirming NRF2 depletion and the reduction in KEAP1 protein." (PMID 40676628, 2025). "Compared to the BA + DDP group, sh-Keap1 intervention disrupted the therapeutic effects of BA/DDP, resulting in decreased body weight and increased tumor volume and weight." (PMID 39061086, 2024). "Nrf2 is activated in the tumor microenvironment by tumor suppressor genes BRCA1 and protein p21 via suppression of Keap1/Nrf2 complex formation, and is inhibited by oncogene Fyn-mediated degradation." (PMID 39407193, 2024). "In this study, we analysed the tumour immune microenvironment in LUAD and LUSC patients stratified by mutant and wild-type KEAP1 status using data obtained from the TCGA cohort." (PMID 38962454, 2024). "KEAP1 mutations are commonly concurrent with KRAS and/or STK11 mutations in NSCLC and confer tolerance to oxidative stress through the KEAP1/NRF2 pathway, promoting tumor progression and drug resistance." (PMID 38949950, 2024). "Overall, using both human and murine tumor models in immunodeficient and immunocompetent mice, we demonstrate that DRP-104 effectively inhibits the growth of KEAP1 mutant lung tumors and, in some cases, results in tumor regression." (PMID 38536921, 2024).
tumor (continued). "Conversely, the downregulated PD-L1 expression by KEAP1 increases CD8+ T cells, thereby promoting anti-tumor immunity." (PMID 38413563, 2024). "In this study, we identified AURKA inhibitors, including MLN8237, which are undergoing clinical trials in various tumor types, including NSCLC, as potential targeted drugs for KEAP1 mutant NSCLC." (PMID 38521813, 2024). "The expression of KEAP1, NFE2L2, and NOX4 were generally higher than normal level of body in more than 20 tumor tissue samples." (PMID 36627482, 2023). "We also quantified tumor GFP fluorescence intensity after anti-CD40 treatment and found significantly higher fluorescence of the tumors grown in the conditional Keap1-KO animals." (PMID 38060331, 2023). "Previous studies have shown that overactivation of the KEAP1/NRF2 signaling pathway can promote the growth and chemoresistance of various tumor cells." (PMID 36719368, 2023). "Some molecules that possess DLG or ETGE motifs or that resemble DLG or ETGE motifs can disrupt the binding of KEAP1 and NRF2, which is recognized as one of the most important mechanisms by which tumor cells adapt to antioxidant activities." (PMID 37525222, 2023). "When p62 competitively binds KEAP1, NRF2 is released and enters the nucleus to activate downstream target gene transcription and promote tumor cell survival." (PMID 37403096, 2023). "We identified KEAP1 and DPP7 as genes controlled by H3K9ac in response to heat shock that can better induce apoptosis in tumor cells when combined with hyperthermia." (PMID 37781518, 2023). "Our results suggest that the combination of KEAP1 and DPP7 with hyperthermia treatment can more effectively inhibit tumor cell growth and induce tumor cell apoptosis." (PMID 37781518, 2023). "In this study, we identified two genes, KEAP1 and DPP7, that showed significant tumor growth delay and enhanced tumor cell apoptosis only when overexpressed in combination with hyperthermia." (PMID 37781518, 2023). "KEAP1 and DPP7 as genes affected by heat-induced inhibition of H3K9ac, and combining them with hyperthermia can better induce apoptosis in tumor cells." (PMID 37781518, 2023). "KEAP1 eviction and NRF2 activation provoke tumor progression and metastasis in lung adenocarcinoma through the activation of BTB and CNC homology 1 (BACH1), which has been implicated in RAS-driven tumor formation." (PMID 37381723, 2023). "Treatment of cells with cisplatin showed that Keap1-mutant SSC9 and patients’ primary tumor cells had resistance to cisplatin compared to Keap1 wild-type cells." (PMID 35945195, 2022). "For other metabolic inhibitors, such as the glutaminase inhibitor telaglenastat, surrogate genetic biomarkers leading to tumor glutamine dependence are being employed (e.g., NRF2/KEAP1)." (PMID 34981784, 2022). "KEAP1 and PIK3CB alterations were also in accordance with the difference tendency in tumor tissue samples." (PMID 35155229, 2022). "Our results demonstrate that BAP1 is a tumor suppressor, which suppresses NRF2 in LUAD by deubiquitinating KEAP1." (PMID 35052618, 2022).
tumor (continued). "In this study, we observed that high levels of Keap1 expression significantly correlated with lower proliferation and migration of LUAD cells and Keap1 knockdown facilitated EMT of tumor cells." (PMID 34466284, 2021). "Based on collective data on NRF2 and KEAP1, there is a growing interest in better defining the therapeutic use of natural obtained or chemically synthesized activators of NRF2 with tumor-suppressing properties." (PMID 33808001, 2021). "In the present study, we also identified CD38-cADPR exhibited a remarkable down-regulation of KEAP1 and upregulation of NRF2 in tumor cells." (PMID 34226519, 2021). "The high expression level of Keap1 protein inhibited the growth and metastasis of LUAD cells and enhanced the sensitivity to chemotherapy, suggesting an anti-tumor effect of Keap1." (PMID 34466284, 2021). "The results showed that the expression of SP1, KEAP1, AIFM2, and NOX4 all increased in tumor tissues." (PMID 34745421, 2021). "RBM47 suppresses Nrf2 activity by upregulating KEAP1 and CUL3, and suppressing some Nrf2 activators, leading to the inhibition of tumor growth in vivo." (PMID 34804951, 2021). "Mechanistically, circKEAP1 competitively binds to miR-141-3p and relive miR-141-3p repression for its host gene, which activated the KEAP1/NRF2 signal pathway, and finally suppresses the tumor progress." (PMID 34136401, 2021). "And in CD38 LLC-bearing-BALB/c-nude mice tumor tissues, it was also confirmed that CD38 KO and MU-bearing-tumor tissues exhibited a higher expression of Keap1 than that of in CD38 WT and OE-bearing-tumor tissues." (PMID 34226519, 2021). "For example, Nrf2 is reported to be activated by tumor-suppressor genes such as BRCA1 and p21 by blocking the formation of the Keap1/Nrf2 complex." (PMID 33466626, 2021). "KEAP1 is a negative regulator of the transcriptional factor NRF2, and KEAP1 inactivation aberrantly activates the NRF2 pathway, conferring a more aggressive tumor phenotype." (PMID 34885068, 2021). "By adding cADPR and 8-Br-cADPR to co-culture tumor cells, we found that cADPR inhibited the expression of KEAP1, but promoted the expression of NRF2 in CD38 KO and MU tumor cells, while 8-Br-cADPR was on the contrary." (PMID 34226519, 2021). "Conclusively, our study has presented functional experiments demonstrating that miR-181d regulated the OGT/KEAP1/NRF2 axis to promote the DDP resistance in vitro and tumor growth in vivo of OC." (PMID 34876558, 2021). "The mRNA expression of KEAP1, HSBP1, SAT1, CISD1, and GPX4 were significantly different between tumor and the adjacent tissues." (PMID 34692692, 2021). "In order to confirm the physiological function of miR-181d/OGT/KEAP1/NRF2, A2780 cell-implanted xenograft tumor models were established to clarify the effect of OGT on tumor formation in mice." (PMID 34876558, 2021). "In conclusion, our study reveals that circKEAP1 competitively binds miR-141-3p to abolish the suppressive effect of miR-141-3p on KEAP1, which results to suppress the NRF2/HDAC4 signal pathway and inhibit tumor progress." (PMID 34136401, 2021). "Many studies have shown that KEAP1 and NRF2 proteins function as tumor suppressors, as their absence leads to tumorigenesis while other work indicates that NRF2 can also promote tumor progression." (PMID 33808001, 2021). "Constitutive NRF2 activation and subsequent ROS suppression resulted from Keap1 deletion in a mouse model of LSCC promote aggressive proliferation, metastasis of tumors, and tumor resistance to oxidative stress, chemo- and radiotherapy." (PMID 34277453, 2021). "In particular, fumarate, that accumulates in FH-deficient tumors as type II CIMP-RCC and HLRCC, can directly succinate both KEAP1 and DJ-1 modulating NRF2, with a different impact on tumor growth and survival." (PMID 33233657, 2020).